GLA (galactosidase alpha)
Diseases named in the same sentence as GLA in open-access papers (continued):
Sharing a sentence is not in itself a finding about the gene and the disease.
Fabry disease (continued). "Fabry disease is a rare X-linked genetic disorder caused by mutations in the GLA gene encoding α-galactosidase A (α-Gal A)." (PMID 39200328, 2024). "Renal pathology features of FSGS can also be identified in patients with Fabry disease, and so we focused our attention on the analysis of all variants located in the coding regions of the GLA gene (NM_000169.3)." (PMID 38338714, 2024). "In Fabry disease, the severity of the symptomatology will depend on the percentage of cells in which the X-chromosome carrying the mutation in the GLA gene remains active." (PMID 38791200, 2024). "The patient, a 26-year-old female at the time of the first study, came to our attention as the daughter of a male patient diagnosed with the c.718_719delAA mutation in the GLA gene, responsible for the classic variant of Fabry disease." (PMID 38791200, 2024). "The inherited disorder Fabry disease (FD) is caused by several hundred mutations in the gene encoding the enzyme α-galactosidase A (GLA)." (PMID 38593151, 2024). "The GLA c.337T > C (p.Phe113Leu) is a known pathogenic variant associated to late-onset Fabry disease phenotype with predominant cardiac manifestations." (PMID 37097439, 2023). "Fabry disease (OMIM 301500) is an X-linked lysosomal storage disease caused by variants in the GLA gene." (PMID 35977816, 2023). "Fabry disease is an X-linked genetic disorder caused by mutations in the GLA gene resulting in a defect of α-galactosidase A (α-Gal)." (PMID 36205882, 2023). "We have also identified P/LP variants in HCM phenocopy genes such as GLA related to Fabry disease and FHL1 related to X-linked muscular dystrophy." (PMID 37178278, 2023). "Fabry disease results from mutations in the α-galactosidase A (GLA) gene, leading to enzyme deficiency and accumulation of globotriaosylceramide in cells of various systems." (PMID 36835039, 2023). "Fabry Disease (FD) is an X-linked lysosomal storage disorder, caused by mutations in the GLA gene, leading to a deficiency in α-galactosidase A enzyme activity." (PMID 37504533, 2023). "The Fabry disease is a X-linked disorder caused by mutations in the GLA gene encoding for α-galactosidase A that catalyzes the hydrolysis of terminal non-reducing α-d-galactose residues in α-D-galactosides." (PMID 36902174, 2023). "Fabry disease (FD) is a rare and progressive lysosomal storage disorder caused by mutations in the GLA gene, which is located on the X chromosome." (PMID 38004189, 2023). "Fabry disease (FD) is a monogenic X-linked lysosomal storage disorder (LSD) caused by mutations in GLA gene, which codifies for the lysosomal enzyme α-galactosidase A (α-Gal A)." (PMID 37514122, 2023). "Fabry disease is a rare X-linked hereditary lysosomal storage disorder caused by mutations in the GLA gene located on Xq22.1 encoding the lysosomal enzyme alpha-galactosidase A (α-Gal A)." (PMID 37020293, 2023). "Fabry disease is a multisystemic, lysosomal storage disease caused by mutations of the GLA gene mapping on chromosome X." (PMID 38254927, 2023). "Fabry disease (FD) is caused by deficiency of the lysosomal enzyme alpha-galactosidase A due to variants in GLA." (PMID 37597335, 2023). "In Fabry disease and Krabbe disease, mutations in the degrading enzymes alpha-galactosidase (GLA) and galactocerebrosidase (GALC) both lead to cardiomyopathy." (PMID 36742461, 2023). "Fabry disease [OMIM:301500] is an X-linked inherited LSD caused by mutations on the α-galactosidase A (GLA) gene on chromosome Xq22." (PMID 37239976, 2023). "Fabry disease (FD) is an X-linked lysosomal disorder wherein pathogenic variants of the GLA gene result in the deficiency of the enzyme α-galactosidase A (α–Gal A) (EC entry 3.2.1.22)." (PMID 37626912, 2023). "Fabry disease, an X-linked genetic disorder, arises mainly from mutations in the GLA gene on the chromosome, presenting with symptoms like proteinuria, reduced glomerular filtration rate, and hematuria." (PMID 38235430, 2023).
Fabry disease (continued). "Fabry disease is an X-linked lysosomal storage disorder caused by insufficient α-galactosidase A (GLA) activity resulting from variants in the GLA gene, which leads to glycosphingolipid accumulation and life-threatening, multi-organ complications." (PMID 37254000, 2023). "Fabry disease is caused by a deficiency of α-galactosidase A (GLA) leading to the lysosomal accumulation of globotriaosylceramide (Gb3) and other glycosphingolipids." (PMID 36959353, 2023). "Fabry’s disease is an X-linked, recessive lysosomal storage disease affecting glycosphingolipid metabolism, caused by a mutation in GLA which encodes alpha-galactosidase A (α-Gal-A)." (PMID 37434208, 2023). "The activity of GLA (deficient in Fabry disease) in the blood was found to be reduced in PD and GBA-PD patients." (PMID 36901867, 2023). "Fabry disease (FD) is an X-linked lysosomal storage disease resulting from mutations of α-galactosidase A (GLA) gene." (PMID 37430370, 2023). "Fabry disease (FD) is an inborn metabolic error caused by a deficiency of alpha-galactosidase A (GLA), a lysosomal hydrolytic enzyme that is inherited in an X-linked manner." (PMID 36329296, 2023). "GLA deficiency due to mutations in the GLA gene causes Fabry disease and leads to an accumulation of neutral glycosphingolipids in lysosomes within various tissues including the nervous system." (PMID 38248833, 2023). "Fabry disease arises from α-galactosidase (GLA) deficiency, which results in the accumulation of globotriaosylceramide (Gb3) and lysoGb3 in the lysosome." (PMID 35784393, 2022). "We report a 60-year-old male patient who was diagnosed with Fabry disease at the age of 34 years with the classic c.730G > A (p.Asp244Asn) variant of the GLA gene and treated with agalsidase beta biweekly." (PMID 36406818, 2022). "Fabry disease is an X-linked lysosomal multisystem storage disorder induced by a mutation in the alpha-galactosidase A (GLA) gene." (PMID 35163813, 2022). "Fabry disease is a rare X-linked lysosomal storage disorder caused by pathogenic variants in the GLA gene, which encodes for the α-galactosidase A enzyme." (PMID 36406818, 2022). "Fabry disease is a rare X-linked inherited lysosomal storage disorder caused by mutations in the GLA gene that encodes the alpha-galactosidase A (α-Gal A) enzyme." (PMID 36013057, 2022). "Fabry disease is caused by mutations in the enzyme protein-coding gene GLA (galactosidase alpha) mapped to the X-chromosome (Xq21.3-q22)." (PMID 36556012, 2022). "Fabry disease (FD) is rare X-linked metabolic lysosomal disorder, caused by pathogenic variants of the gene GLA." (PMID 35840992, 2022). "Fabry disease is associated with the reduced activity of lysosomal galactosidase A (GLA), an enzyme involved in the catabolism of globotriaosylceramide (Gb3)." (PMID 36386210, 2022). "GLA deficiency in patients with Fabry disease results in abnormal glycosphingolipid metabolism and the progressive accumulation of Gb3." (PMID 36386210, 2022). "Fabry disease (FD) is an X-linked inherited disorder caused by mutations in the GLA gene encoding enzyme alpha-galactosidase A (α-Gal A)." (PMID 35212703, 2022). "Fabry disease (FD) is a lysosomal storage disorder (LSD) caused by mutations in the gene GLA in the X chromosome, which is responsible for encoding the lysosomal enzyme α-Galactosidase A (α-Gal A)." (PMID 35889565, 2022). "Anderson–Fabry disease (FD) is a rare (approximate incidence 1:40,000) genetic lysosomal storage disorder caused by a mutation in the alpha-galactosidase A (GLA) gene with an X-linked inheritance." (PMID 35160031, 2022). "Fabry disease (FD) is a rare X-linked lysosomal disorder characterized by deficiency of α-galactosidase A (α-GalA), encoded by the GLA gene." (PMID 35725559, 2022). "We report a 60-year-old male patient who was diagnosed with Fabry disease with the classic c.730G > A (p.Asp244Asn) variant of the GLA gene at 34 years of age." (PMID 36406818, 2022).
Fabry disease (continued). "Fabry disease is a monogenic disease characterized by a deficiency or loss of the α-galactosidase A (GLA)." (PMID 36386210, 2022). "For boys with clinical signs and symptoms of Fabry disease, it is recommended to investigate α-Gal A activity, a value of < 1% being highly suggestive of Fabry disease and molecular testing for GLA gene mutation is necessary." (PMID 35722479, 2022). "For example, Fabry disease is caused by the accumulation of globotriaosylceramide in cells due to alpha-galactosidase A (GLA) deficiency." (PMID 35052837, 2022). "This compound has shown clinical efficacy on different clinical manifestations of Fabry disease and is now approved for the treatment of patients with amenable GLA gene mutations." (PMID 33459519, 2021). "Fabry disease (FD) is one of the commonest Lysosomal Storage Disorders (LSDs) and is caused by mutations in the alpha-galactosidase A gene (GLA) from which results a deficient activity of the lysosomal hydrolase alpha- galactosidase A (α-Gal A)." (PMID 33530161, 2021). "Fabry disease (FD) is an X-linked multisystemic lysosomal storage disease due to a deficiency of α-galactosidase A (GLA/AGAL)." (PMID 34917096, 2021). "Recently, a novel GLA mutation, c.270C>G (p.Cys90Trp), was identified in a Lithuanian family with a classical form of Fabry disease in heterozygous women with predominant cardiac phenotype." (PMID 33572752, 2021). "Fabry disease (FD) is an X-linked, inborn error of glycosphingolipid metabolism resulting from mutations in the GLA gene in the X chromosomal region Xq22.1 that leads to deficient activity of the lysosomal enzyme, alpha-galactosidase A." (PMID 34067605, 2021). "Fabry (sometimes referred to as Anderson–Fabry) disease is a progressive X-linked lysosomal storage disorder caused by a mutation in the GLA gene, encoding the lysosomal hydrolase α-galactosidase A (α-Gal A)." (PMID 34575277, 2021). "Fabry disease is an X-linked lysosomal storage disease caused by a mutation in the galactosidase alpha (GLA) gene." (PMID 34654880, 2021). "Fabry disease is a rare X-linked lysosomal storage disorder caused by mutations in the GLA gene, leading to deficient α-galactosidase A activity and, consequently, to glycosphingolipid accumulation in a wide variety of cells." (PMID 34959703, 2021). "To confirm STX staining is selective for Gb3, we used HeLa cells lacking alpha‐galactosidase A (HeLa‐GLA‐KO), a cell model of Anderson‐Fabry disease that results from mutations in the GLA gene leading to Gb3 accumulation (Fig EV1B)." (PMID 34411438, 2021). "Fabry disease (FD) is caused by mutations in the α-galactosidase A (GLA) gene encoding the lysosomal AGAL enzyme." (PMID 34768768, 2021). "Anderson–Fabry disease (AFD) is a rare X-linked inborn error of glycosphingolipid catabolism that results from mutations in the alpha-galactosidase A gene (GLA) at Xq22." (PMID 34576250, 2021). "Fabry disease (FD) is an X-linked inherited disorder caused by mutations in the GLA gene, which encodes the lysosomal enzyme α-galactosidase A (α-Gal A)." (PMID 34679477, 2021). "Ile239Met mutation in the GLA gene occurs in a family with a predominant cardiac phenotype of Fabry disease." (PMID 33572752, 2021). "Fabry disease is an X-linked multisystemic disorder caused by pathogenic GLA variants that result in functional deficiency of the lysosomal enzyme α-galactosidase A (α-Gal A)." (PMID 33914257, 2021). "Lysosomal accumulation of globotriaosylceramide (Gb3) is the element characterizing Fabry disease due to a hereditary deficiency α-galactosidase A (GLA) enzyme." (PMID 34576250, 2021). "Fabry disease is a rare inherited disorder caused by a mutation in the gene for the enzyme galactosidase alpha (GLA)." (PMID 34654880, 2021). "Fabry disease (FD) is an X-linked lysosomal disorder arising from molecular variants in the GLA gene producing inadequate α-galactosidase A (AGA) activity." (PMID 33335842, 2020).
Fabry disease (continued). "Pharmacological chaperone therapy with the novel chaperone DGJ in Fabry disease depends on the biochemical responsiveness of the GLA gene variant." (PMID 32023956, 2020). "In Fabry disease, one of the lysosomal storage diseases, GLA mutations defect α‐galactosidase A (α‐GALA) in hydrolyzing the terminal α‐galactosyl moieties from GSLs, and bring about accumulation of Gb3 in cells, particularly in kidneys, heart and skin." (PMID 33205006, 2020). "Fabry disease (FD) is a lysosomal disease in which mutations affect the GLA gene located on the X chromosome." (PMID 31871893, 2020). "Fabry disease is a rare X-linked lysosomal storage disease arising from a deficiency in alpha-galactosidase A (GLA) that results in the accumulation of glycosphingolipids." (PMID 33138098, 2020). "Next, we plan to analyze splicing abnormalities in the OCRL gene causing Lowe syndrome and in the GLA gene causing Fabry disease, using the same approach." (PMID 32201916, 2020). "Fabry disease is an X-linked lysosomal storage disorder caused by mutations in the GLA gene encoding the α-galactosidase A enzyme." (PMID 32854306, 2020). "Fabry disease (FD) is a rare X-linked glycosphingolipidosis caused by pathogenic alleles of the gene encoding the lysosomal enzyme alpha-galactosidase (GLA; OMIM*300644)." (PMID 32784589, 2020). "A more recent study also reported a decreased activity of alpha-galactosidase A in Parkinson’s disease (encoded by the GLA gene that deficiency is associated to Fabry disease)." (PMID 33069254, 2020). "Fabry disease, an X-linked recessive lysosomal disease, results from mutations in the GLA gene encoding lysosomal α-galactosidase A (α-Gal A)." (PMID 33036426, 2020). "Fabry disease is a rare X-linked lysosomal storage disorder caused by mutations in the GLA gene (position Xq22), which encodes the a-galactosidase A (a-GAL) enzyme." (PMID 32227072, 2020). "This was possible for GAA, GBA, and IDUA, however, for GLA only when targeting the positive identification of males with Fabry disease while accepting the inability to identify all female GLA mutation carriers." (PMID 32802993, 2020). "Patients with milder GLA mutations have late onset Fabry disease and circulating lyso-Gb3 around 3−18 nM, while severe GLA mutations causing classical Fabry disease and nephropathy display lyso-Gb3 levels in the 80−300 nM range in males." (PMID 33203029, 2020). "Fabry disease (FD - OMIM 301500) is a lysosomal storage disorder caused by pathogenic variants in the X-linked GLA gene (Xq22.1)." (PMID 31996269, 2020). "In general, Fabry disease causing-variants are divided into two different types: those that affect the active site of the enzyme α-galactosidase (GLA) and those that adversely affect the stability of the folded protein." (PMID 32883051, 2020). "Fabry disease is an X‐linked hereditary disease caused by mutations in GLA, which encodes the lysosomal enzyme α‐galactosidase A1; approximately 840 GLA mutations have been identified." (PMID 32617522, 2020). "In Taiwan, newborn screening for Pompe disease and Fabry disease (due to a deficiency of alpha-galactosidase A, GLA) has been ongoing since 2005 and 2006, respectively." (PMID 32802993, 2020). "Fabry Disease is a X-linked genetic lysosomal storage disorder caused by mono- or biallelic LoF mutations in the GLA gene and affects men and women." (PMID 33324928, 2020). "Migalastat is an oral agent that acts as a pharmacologic chaperone for α-Gal A. In previous studies, migalastat provided clinical benefit with good tolerability in patients with Fabry disease and amenable GLA mutations." (PMID 31889231, 2020). "In Fabry disease, the α-galactosidase GLA is deficient, leading to the accumulation of Galα-containing globosides, and affecting blood group B determinants of GSLs and glycoproteins." (PMID 32961778, 2020).
Fabry disease (continued). "Fabry disease (FD) is a rare genetic lysosomal storage disorder caused by mutations in the GLA gene (OMIM#300644), and is inherited in an X-linked manner." (PMID 33003611, 2020). "Fabry disease (FD) is an X-linked recessive lysosomal storage disease caused by a deficiency of the α-galactosidase A enzyme (encoded by the GLA gene)." (PMID 32991443, 2020). "Mutations in the GLA gene cause Fabry disease, an X-linked lysosomal disease characterized by progressive accumulation of GL-3 in cells." (PMID 33036426, 2020). "Fabry disease is an inherited metabolic disorder due to a mutation in the gene that encodes lysosomal enzyme alpha-galactosidase A (GLA)." (PMID 33521063, 2020). "Fabry disease (FD) (OMIM 301500) is an X‐linked disorder of glycosphingolipid catabolism caused by a deficiency of the lysosomal enzyme alpha‐galactosidase A (GLA)." (PMID 31169365, 2019). "We and others have observed increased levels of oxidative/nitrosative stress in tissues of patients with Fabry disease and GLA-deficient mice." (PMID 31120949, 2019). "Fabry disease is an X-linked lysosomal disorder caused by mutations in the alpha-galactosidase A (GLA) gene." (PMID 31071994, 2019). "Fabry disease (FD) is an X-linked lysosomal storage disorder caused by mutations of the GLA gene, followed by deficiency in α-galactosidase A (α-gal) activity." (PMID 31847900, 2019). "Fabry disease (FD) is an inherited lysosomal storage disorder (LSD) caused by mutations in the GLA gene on the X chromosome, leading to the deficiency of α-galactosidase A (α-gal A)." (PMID 31378672, 2019). "Fabry disease is caused by deficiency in GLA activity, and the leading ERT is Fabrazyme (Sanofi Genzyme) produced in CHO cells." (PMID 31040271, 2019). "One of these cardiomyopathies is Fabry disease (FD), which is caused by alpha-galactosidase A (GLA) deficiency leading to accumulation of globotriaosylceramide (Gb3) in several tissues." (PMID 30965672, 2019). "Fabry disease (FD) is an X‐linked disorder of glycosphingolipid catabolism caused by a deficiency of the lysosomal enzyme alpha‐galactosidase A (GLA)." (PMID 31169365, 2019). "Fabry disease is caused by the genetic mutations in the alpha-galactosidase-A gene (GLA-gene), located on the long arm of the X-chromosome (Xq22.1)." (PMID 31484286, 2019). "Fabry disease (FD) is an X‐linked lysosomal storage disorder caused by enzyme Alpha‐Galactosidase A (α‐Gal‐A) deficiency, due mutations in GLA gene." (PMID 31392112, 2019). "Fabry disease, a reported mimic of multiple sclerosis (MS), is an X-linked inherited lysosomal storage disease due to a GLA-gene defect." (PMID 31163654, 2019). "Fabry disease (OMIM #301500) is an X-linked lysosomal storage disorder caused by pathogenic variants in the GLA gene (OMIM #300644; HGNC 4296) encoding the lysosomal enzyme α-galactosidase." (PMID 30775256, 2019). "Fabry disease (FD) is an X‐linked disorder caused by mutations in GLA, coding for α‐galactosidase A enzyme (α‐Gal A)." (PMID 31393666, 2019). "Fabry disease (FD) results from X-linked inheritance of a mutation in the GLA gene, encoding for alpha galactosidase A, and is characterized by heterogeneous clinical manifestations." (PMID 29621274, 2018). "Fabry disease [MIM: 301500] is a hereditary disorder of the glycosphingolipid metabolism caused by mutations in the alpha-galactosidase A (GLA) gene located on the X chromosome." (PMID 30038331, 2018). "To test this relationship, we administered a self-report and family history questionnaire to determine the prevalence of PD in Fabry disease patients and family members with likely pathogenic alpha-galactosidase A (GLA) mutations." (PMID 29159076, 2018). "Fabry disease is a lysosomal storage disorder resulting from impaired alpha-galactosidase A (α-Gal A) enzyme activity due to mutations in the GLA gene." (PMID 30038331, 2018).